IL1RAPL2 (interleukin 1 receptor accessory protein like 2)
Synonyms: IL1RAPL-2; IL-1R9; TIGIRR-1; IL1R9
Tractability: Antibody: its Gene Ontology location is reachable by antibodies, with high confidence; UniProt predicts a signal peptide or a membrane-spanning region; the Human Protein Atlas places it where antibodies can reach.
Gene: Protein-coding gene on chromosome X (104,566,199 to 105,767,829, forward strand). Ensembl gene ENSG00000189108.
Subcellular location: Membrane
Subcellular location (Human Protein Atlas): Plasma membrane
Pathways (Reactome):
Neuronal System: Receptor-type tyrosine-protein phosphatases
Gene Ontology:
Molecular function: protein binding; interleukin-1 receptor activity; cytokine receptor activity; interleukin-1, type II, blocking receptor activity; NAD+ nucleosidase activity, cyclic ADP-ribose generating
Biological process: regulation of presynapse assembly; cell surface receptor signaling pathway; central nervous system development; cytokine-mediated signaling pathway; nervous system development; signal transduction
Cellular component: glutamatergic synapse; cell surface; plasma membrane; membrane
Homologues: Orthologues: chimpanzee IL1RAPL2 (99% identical), macaque IL1RAPL2 (98% identical), pig IL1RAPL2 (97% identical), rabbit IL1RAPL2 (96% identical), mouse Il1rapl2 (94% identical), rat Il1rapl2 (92% identical), guinea pig IL1RAPL2 (75% identical), tropical clawed frog il1rapl2 (74% identical), zebrafish il1rapl2 (65% identical), dog IL1RAPL2 (60% identical). Paralogues in human: IL1RAPL1 (62% identical), IL1RAP (29% identical), IL18RAP (25% identical), IL18R1 (23% identical), IL1R1 (22% identical), IL1RL1 (21% identical), IL1RL2 (20% identical), IL1R2 (16% identical), SIGIRR (9% identical), LAG3 (8% identical).
Diseases named in the same sentence as IL1RAPL2 in open-access papers:
IL1RAPL2 is named in the same sentence as 10 diseases in open-access papers, as found by Europe PMC text mining. Sharing a sentence is not in itself a finding about the gene and the disease. The quoted sentences say what the papers report.
autism (3 papers, 2011 to 2025). Persistent deficits in social interaction and communication and interaction as well as a markedly restricted repertoire of activity and interest as well as repetitive patterns of behavior. "Researchers in other studies have also suggested that IL1RAPL1, which is closely related to the IL1RAPL2 gene, identified in this study, is associated with autism." (PMID 22050706, 2011). "IL1RAPL2 is closely related to IL1RAPL1, which has been associated with mental retardation, autism and psychiatric disorders, all of which are conditions associated with PTD." (PMID 23613933, 2013). "Because both the Il1rapl2+ L5 IT neurons and the Foxp2+ L6 CT neurons in the mPFC have the most number of differentially expressed GWAS genes for bipolar disorder and autism, they might be involved in regulating aspects of social behaviors." (PMID 40267197, 2025).
Duchenne muscular dystrophy (1 paper, 2011). Duchenne muscular dystrophy (DMD) is a neuromuscular disease characterized by rapidly progressive muscle weakness and wasting due to degeneration of skeletal, smooth and cardiac muscle. "We identified SNP rs721699 in the Duchenne muscular dystrophy gene Dystrophin (DMD) [OMIM:300377] in the overall test and SNPs rs9887672, rs10218388 and rs5962575 in the IL-1 receptor accessory protein-like 2 (IL1RAPL2) gene [OMIM:300277] in the male test." (PMID 22050706, 2011).
viral infection (1 paper, 2022). "In the context of the viral infection, IL1RAPL2 could act as an accessory protein or cofactor for cellular receptors and could influence viral attachment and/or dissemination." (PMID 35931765, 2022).
head and neck tumors (1 paper, 2024). "In this study, it was found that IL-1α, IL-1β, IL1R1, IL1RL1, IL1F10, IL33, CASP1, and AIM2 were highly expressed in head and neck tumors, while IL1RN, IL1RAPL1, IL1RAPL2, IL18BP, IL18R1, and IL18RAP were low in expressed, which is consistent with previous literature." (PMID 39461030, 2024).
kidney disease (1 paper, 2023). "There is a lack of studies about IL1RAPL2 and PGR in relation to kidney disease." (PMID 37091784, 2023).
neurological diseases (1 paper, 2023). "By consulting relevant literature, 6 genes related to neurodevelopmental and neurological diseases (GPC5, CA10, DSCAM, IL1RAPL2, CNTN2, and SPOCK3) were verified by ELISA method." (PMID 37539343, 2023). "Finally, six genes/proteins related to neurodevelopmental and neurological diseases (GPC5, CA10, DSCAM, IL1RAPL2, CNTN2, and SPOCK3) were verified by ELISA." (PMID 37539343, 2023).
IL1RAPL2 also shares sentences with these, for which no sentence is quoted: psychiatric diseases (2 papers); Anxiety (1); bipolar disorder (1); mental retardation (1).